AGPAT4 (1-acylglycerol-3-phosphate O-acyltransferase 4)
Description:
Converts 1-acyl-sn-glycerol-3-phosphate (lysophosphatidic acid or LPA) into 1,2-diacyl-sn-glycerol-3-phosphate (phosphatidic acid or PA) by incorporating an acyl moiety at the sn-2 position of the glycerol backbone (By similarity). Exhibits high acyl-CoA specificity for polyunsaturated fatty acyl-CoA, especially docosahexaenoyl-CoA (22:6-CoA, DHA-CoA) (By similarity).
Synonyms: LPAAT-delta; dJ473J16.2; LPAAT4; LPLAT4; 1-AGPAT4
Tractability: Antibody: UniProt predicts a signal peptide or a membrane-spanning region. PROTAC: ubiquitination databases record sites on it; its protein half-life has been measured.
Gene: Protein-coding gene on chromosome 6 (161,129,967 to 161,274,095, reverse strand). Ensembl gene ENSG00000026652.
Subcellular location: Endoplasmic reticulum membrane
Subcellular location (Human Protein Atlas): Golgi apparatus; Nucleoli; Vesicles
Pathways (Reactome):
Metabolism: Synthesis of PA
Gene Ontology:
Molecular function: protein binding; 1-acylglycerol-3-phosphate O-acyltransferase activity; acyltransferase activity; lysophosphatidic acid acyltransferase activity
Biological process: phosphatidic acid biosynthetic process; phospholipid biosynthetic process; CDP-diacylglycerol biosynthetic process; glycerophospholipid metabolic process; phospholipid metabolic process
Cellular component: endoplasmic reticulum; endoplasmic reticulum membrane; mitochondrial outer membrane
Genetic constraint (gnomAD): Loss-of-function variants: 15 observed, 50.11 expected, observed/expected ratio (o/e) 0.3, 90% interval 0.2 to 0.46. The upper end of that interval is the gene's LOEUF score, 0.46, which puts it in group 2 of 6, group 1 being the genes least tolerant of losing a copy. Missense variants: 314 observed, 500.99 expected, observed/expected ratio (o/e) 0.63, 90% interval 0.57 to 0.69. Synonymous variants: 178 observed, 208.92 expected, observed/expected ratio (o/e) 0.85, 90% interval 0.75 to 0.96.
Homologues: Orthologues: chimpanzee AGPAT4 (99% identical), dog AGPAT4 (92% identical), pig AGPAT4 (92% identical), guinea pig AGPAT4 (87% identical), mouse Agpat4 (86% identical), rat Agpat4 (86% identical), tropical clawed frog agpat4 (76% identical), zebrafish agpat4 (68% identical), macaque AGPAT4 (62% identical), Drosophila melanogaster Agpat3 (39% identical), Drosophila melanogaster Agpat4 (36% identical). Paralogues in human: AGPAT3 (61% identical), LCLAT1 (23% identical), AGPAT5 (21% identical), LPGAT1 (19% identical).
Diseases named in the same sentence as AGPAT4 in open-access papers:
AGPAT4 is named in the same sentence as 13 diseases in open-access papers, as found by Europe PMC text mining. Sharing a sentence is not in itself a finding about the gene and the disease. The quoted sentences say what the papers report.
colorectal cancer (9 papers, 2020 to 2025). A primary or metastatic malignant neoplasm that affects the colon or rectum. "Elevated AGPAT4 expression in cancer tissues is associated with poorer survival rates in colorectal cancer patients." (PMID 41149035, 2025). "In colorectal cancer, regulation of the Agpat4/LPA/p38/p65 axis has been reported to control repolarization to M1-like TAMs, T cell activity, and tumor progression." (PMID 39199574, 2024). "Agpat4/LPA axis in colorectal cancer cells has been validated to regulate p38/p65 signaling-dependent macrophage polarization." (PMID 35548052, 2022). "In colorectal cancer tumors, increased AGPAT4 expression leads to the release of lysoPA, activating macrophages and polarizing them into anti-tumor M1 macrophages, suggesting therapeutic potential in colorectal cancer." (PMID 38893234, 2024). "In colorectal cancer (CRC), however, suppressing 1-acylglycerol-3-phosphate O-acyltransferase 4 (Agpat4) can stimulate the production of LPA from CRC cells, and LPA polarizes macrophages into M1-like phenotypes through LPA1 and LPA3." (PMID 37569902, 2023). "On the contrary, in colorectal cancer (CRC), silencing 1-acylglycerol-3-phosphate O-acyltransferase 4 (Agpat4) induced the production of LPA from CRC cells and consequently polarized peritoneal macrophages in a M1 phenotype through LPAR1 and LPAR3." (PMID 32397679, 2020). "Silencing AGPAT4 releases lysophosphatidic acid from cancer cells, polarizing macrophages to an M1‐like phenotype, which promotes CD4+ and CD8+ T cell infiltration and activation, influencing colorectal cancer progression." (PMID 40119647, 2025). "AGPAT4, ENTPD1, HADHB, CA12, CA9 was reported in colorectal cancer." (PMID 33815132, 2021).
breast carcinoma (2 papers, 2022). "AGPAT4 was identified, together with AGPAT3, among breast cancer-expressed genes involved in endo-/exocytosis (EEC) in a reanalysis of the results from three independent genome-wide association studies." (PMID 35008394, 2022).
colon cancer (2 papers, 2020 to 2024). "Notably, flow cytometry in a previous study demonstrated that the infiltration of M1-like TAM was reduced in tissues from colon cancer patients who exhibited high Agpat4 expression." (PMID 38954021, 2024). "The Agpat4/LPA/p38/p65 axis emerges as a promising therapeutic target in colon cancer." (PMID 38954021, 2024).
endometriosis (1 paper, 2024). The growth of functional endometrial tissue in anatomic sites outside the uterine body. "Our investigation identified 11 genes associated with endometriosis risk, with AGPAT4 and COMT emerging as pivotal biomarkers through machine learning analysis." (PMID 38850428, 2024). "Interestingly, our study did not reveal significant expression of COMT, another gene previously implicated in endometriosis, suggesting a more prominent role for AGPAT4 in the disease’s pathogenesis." (PMID 38850428, 2024). "Our study investigates AGPAT4’s involvement in endometriosis pathogenesis, aiming to unveil new therapeutic targets." (PMID 38850428, 2024). "By elucidating the mechanistic pathways and biological impacts of AGPAT4, this research aims to underscore its therapeutic promise in mitigating endometriosis, potentially revolutionizing treatment paradigms." (PMID 38850428, 2024). "AGPAT4 exhibited significant upregulation in both ectopic tissues and serum samples from patients with endometriosis." (PMID 38850428, 2024). "Our research not only elucidates the genetic underpinnings of endometriosis but also positions AGPAT4 as a central figure in potential therapeutic strategies." (PMID 38850428, 2024). "Plasma levels of the AGPAT4 protein in endometriosis patients were significantly higher compared to the control group (P < 0.01)." (PMID 38850428, 2024). "Molecular docking analyses further underscored a substantive interaction between AGPAT4 and Wnt3a.Our study highlights AGPAT4’s key role in endometriosis, influencing endometrial stromal cell behavior, and identifies AGPAT4 pathways as promising therapeutic targets for this condition." (PMID 38850428, 2024). "In the context of endometriosis, the function of AGPAT4 is yet to be fully unraveled." (PMID 38850428, 2024). "Five Mendelian randomization methods indicated that both AGPAT4 and COMT could serve as risk genes for endometriosis." (PMID 38850428, 2024). "The discovery that AGPAT4 is predominantly expressed in epithelial and tissue stem cells, as revealed by single-cell transcriptomics, coupled with its elevated expression in the peripheral blood plasma of individuals with endometriosis and its pronounced presence in ectopic versus eutopic tissues." (PMID 38850428, 2024). "However, the mechanism of action of AGPAT4 in endometriosis is unknown." (PMID 38850428, 2024).
immune deficiency (1 paper, 2020). "Interestingly, we found that the tumor suppression induced by Agpat4 silencing disappeared in the context of immune deficiency." (PMID 32296017, 2020).
Intellectual disability (1 paper, 2022). "The role of AGPAT4 in higher brain function is supported by a genetic study that identified abnormalities in the AGPAT4 gene locus (a duplication overlapping MAP3K4 and AGPAT4) in patients with non-syndromic intellectual disability." (PMID 35008394, 2022).
ovarian endometriosis (1 paper, 2024). A non-neoplastic disorder characterized by the growth of endometrial tissue in the ovaries. "Notably, AGPAT4 protein expression in the ectopic endometrium of ovarian endometriosis was markedly elevated compared to the eutopic tissue group (P < 0.05)." (PMID 38850428, 2024).
thyroid cancer (1 paper, 2026). "Protein-protein interaction (PPI) network and functional enrichment analyses revealed that AGPAT4 is involved in key pathways associated with thyroid cancer progression." (PMID 41514378, 2026).
tumor (9 papers, 2020 to 2026). "Agpat4-regulated LPA release from CRC cells activated T cells through p38/p65 signaling-mediated M1 polarization of tumor-associated macrophages and subsequently triggered an antitumor response." (PMID 32296017, 2020). "In line with the role of Agpat4 in MC-38 tumors, Agpat4 deficiency markedly suppressed CT-26 tumor progression in the peritoneal and subcutaneous xenograft models." (PMID 32296017, 2020). "AGPAT4 exhibited robust efficacy in distinguishing tumor tissues from normal tissues, with an area under the receiver operating characteristic curve (AUC) of 0.973." (PMID 41514378, 2026). "It has been reported that a high expression of AGPAT4 in tumor cells can reduce the release of lysophosphatidic acid (LPA)." (PMID 35844514, 2022). "In CRC patients, RNA-sequencing analysis revealed that AGPAT4 expression was increased in tumor samples compared to paracarcinoma tissues and predicted poor survival." (PMID 35008394, 2022). "This appears to be, at least partly, mediated by the increased release of LPA from CRC cells upon AGPAT4 knockdown, which activates a systemic antitumor response via the shaping of the immune tumor microenvironment." (PMID 35008394, 2022). "We also demonstrated that the Agpat4 silencing-induced suppression of MC-38 tumor growth was fully prevented by treatment with p38 or NF-κB inhibitors." (PMID 32296017, 2020). "Silencing AGPAT4 in cancer cell lines led to inhibited tumor growth in various models, suggesting that AGPAT4 might influence cancer progression through tumor microenvironment modulation ​." (PMID 38850428, 2024). "Furthermore, silencing Agpat4 induces lysophosphatidic acid (LPA) released from tumor cells, which subsequently promotes p38/p65 phosphorylation through LPA receptors 1 and 3, resulting in M1 polarization and inhibition of tumor progression." (PMID 38606362, 2024). "Similarly, the tumor suppression induced by Agpat4 silencing in immunocompetent mice was fully prevented by anti-CD8 or anti-CD4 neutralizing antibodies." (PMID 32296017, 2020). "In this study, FABP4, PPARGC1A, AGPAT4, ALDH1A1, and GPAT3 were identified as downregulated tumor suppressor genes in TC, whereas TGFA was recognized as an oncogene." (PMID 40119647, 2025).
cancer (7 papers, 2017 to 2025). A tumor composed of atypical neoplastic, often pleomorphic cells that invade other tissues. "In CRC patients, the expression of AGPAT4 in cancer tissues was positively correlated with the size and stages of primary tumors." (PMID 32296017, 2020). "Notably, higher expression of AGPAT4 in the cancer tissues of CRC patients predicted worse survival." (PMID 32296017, 2020). "Agpat4-regulated production of LPA from CRC cells signals through the LPAR1/3 and p38/p65 pathways in macrophages to stimulate M1-dependent T-cell activation and cancer suppression." (PMID 32296017, 2020). "In addition to AGPAT4, a non-protein-coding AGPAT4 intronic transcript, lncRNA AGPAT4-IT1 was also identified to have a potential role in cancer pathogenesis." (PMID 35008394, 2022).
adenocarcinoma (1 paper, 2009). A common cancer characterized by the presence of malignant glandular cells. "Additionally, 1-acylglycerol-3-phosphate O-acyltransferase 4 also known as lysophosphatidic acid acyltransferase was −5.0-fold down regulated in adenocarcinomas." (PMID 19812696, 2009).
AGPAT4 also shares sentences with these, for which no sentence is quoted: atherosclerosis (1 paper); triple-negative breast carcinoma (1).